GK (glycerol kinase)
Description:
Kinase that plays a key role in glycerol metabolism, catalyzing its phosphorylation to produce sn-glycerol 3-phosphate. Sn-glycerol 3-phosphate is a crucial intermediate in various metabolic pathways, such as the synthesis of glycerolipids and triglycerides, glycogenesis, glycolysis and gluconeogenesis.
Synonyms: GK1; GKD
Tractability: Antibody: UniProt predicts a signal peptide or a membrane-spanning region. PROTAC: ubiquitination databases record sites on it; its protein half-life has been measured.
Target class: Enzyme; Transferase
Gene: Protein-coding gene on chromosome X (30,653,359 to 30,731,462, forward strand). Ensembl gene ENSG00000198814.
Subcellular location: Mitochondrion outer membrane; Nucleus; Cytoplasm, cytosol; Mitochondrion outer membrane (Isoform 3); Cytoplasm, cytosol (Isoform 4)
Pathways (Reactome):
Metabolism: Triglyceride biosynthesis
Gene Ontology:
Molecular function: glycerol kinase activity; protein binding; kinase activity; phosphotransferase activity, alcohol group as acceptor
Biological process: glycerol metabolic process; glycerol-3-phosphate biosynthetic process; triglyceride metabolic process; triglyceride biosynthetic process; carbohydrate metabolic process; glycerol catabolic process; glycerol-3-phosphate metabolic process
Cellular component: extracellular exosome; mitochondrion; nucleus; cytosol; mitochondrial outer membrane
Gene-disease validity (ClinGen):
ClinGen rates the evidence that GK causes each of these diseases.
inborn glycerol kinase deficiency (X-linked): Definitive. An acquired metabolic disease that has its basis in the disruption of glycerol kinase activity.
Homologues: Orthologues: macaque GK (99% identical), guinea pig Gk (98% identical), mouse Gk (97% identical), rat Gk (97% identical), chimpanzee GK (94% identical), tropical clawed frog gk (85% identical), zebrafish GK2 (75% identical), Drosophila melanogaster Gk2 (47% identical), Caenorhabditis elegans R11F4.1 (45% identical), Drosophila melanogaster CG8298 (41% identical). Paralogues in human: GK3 (97% identical), GK2 (87% identical), GK5 (31% identical), FGGY (20% identical), SHPK (15% identical), XYLB (14% identical).
Diseases named in the same sentence as GK in open-access papers:
GK is named in the same sentence as 87 diseases in open-access papers, as found by Europe PMC text mining. Sharing a sentence is not in itself a finding about the gene and the disease. The quoted sentences say what the papers report.
diabetes (9 papers, 2008 to 2026). "Given the importance of the GK rat as a model for diabetes, this suggests that many GK/BN alleles across the genome, and that segregate in the cross, contribute to the metabolic and inflammatory mechanisms described in human diabetes." (PMID 27646706, 2016). "Of these, one with lecithin-cholesterol acyltransferase deficiency and another with Kearns-Sayre syndrome had diabetes, and one with glycerol kinase deficiency had glucocorticoid deficiency." (PMID 27086477, 2016). "We have developed a QTL substitution congenic strain containing GK alleles across a 110 cM region of RNO1 covering known diabetes and obesity QTLs Nidd/gk1, transferred onto a Brown-Norway (BN) genetic background." (PMID 18698428, 2008). "Dorzagliatin restored the hepatic GK expression in diabetes rats, increased the numbers of insulin-secreting cells in the pancreas, and improved glycemic control after 28-day treatment." (PMID 36918550, 2023). "Importantly, GK‐AAV8‐SCAMP5 rats demonstrated higher plasma insulin levels, improved glucose tolerance, and progressively decreased blood glucose levels compared to GK‐vehicle rats, suggesting the remission of diabetes." (PMID 40953307, 2025).
Hyperglycemia (9 papers, 2009 to 2024). An increased concentration of glucose in the blood. "This may explain the association of diabetes type 2/hyperglycemia with cardiovascular disease as found in both humans and hyperglycemic mice, including the E3L.GK+/− mice." (PMID 30949516, 2019). "The potential therapeutic benefit of targeting glycerol kinase for hyperglycemia and hyperlipidemia should be further investigated, given the current and increasing prevalence of cardiometabolic diseases globally." (PMID 39512433, 2024). "It has been reported that a substantial reduction of hepatic GK expression in T2D patients correlated with their hyperglycemia and hepatic insulin resistance." (PMID 36918550, 2023). "In the present study, we evaluated the E3L.GK+/− mouse as an animal model for diet-induced hyperlipidemia and hyperglycemia and the pathological consequences thereof." (PMID 30949516, 2019). "Previously, the GK+/−ApoE−/− mouse model has been developed as a model combining hyperlipidemia and hyperglycemia, which had impaired glucose tolerance and a minimal increase of atherosclerosis relative to ApoE−/− mice." (PMID 30949516, 2019). "To explore the effects of hyperglycemia in advanced and fibrous carotid atherosclerotic plaques, induced by a shear stress modifier, we used ApoE−/− GK+/− mice with ApoE−/− mice as controls." (PMID 29760458, 2018). "Potential therapeutic strategies could include glycerol kinase inhibitors to mitigate hyperglycemia in an insulin‐independent manner." (PMID 39512433, 2024). "Interestingly, glucose and insulin levels were not affected by the diet but remained stable representing mild hyperglycemia in the E3L.GK+/− and GK+/− mice (10.4 ± 1.4 mmol/L and 14.1 ± 2.6 mmol/L at the end point, respectively)." (PMID 30949516, 2019). "To further investigate how hyperglycemia affects atherosclerotic plaque progression in the ApoE−/− GK+/− mice we analyzed the macrophage and T-cell contents in plaques by immunohistochemistry, as well as measured the levels of monocytes and Tregs in blood by flow cytometry." (PMID 29760458, 2018). "Furthermore, the absence of diabetes-induced increase in lipid levels in the ApoE−/− GK+/− mouse makes it an appropriate model to isolate the effects of hyperglycemia on atherosclerotic plaque development." (PMID 29760458, 2018). "Thus, ApoE−/− GK+/− mice are appropriate as a model to study the effect of hyperglycemia per se on arterial repair and atherosclerotic plaque formation." (PMID 29760458, 2018). "While hyperglycemia itself is well recognized to be deleterious for EC, other factors, such as hyperlipidemia and insulin resistance, which can precede hyperglycemia, might also be able to mediate EC in GK/Par islets." (PMID 19654863, 2009). "Subdividing the samples by age groups clearly show that anti-GK and anti-citrullinated-GK IgG arise early in NOD mice, by 4–6 weeks of age, and before the onset of hyperglycemia." (PMID 35388005, 2022). "The objective of this study was to develop a translational mouse model for the metabolic syndrome and diabetic complications by combining diet-induced dyslipidemia and hyperglycemia, with plasma levels translatable to the human situation: the APOE∗3Leiden.GK+/− mouse (E3L.GK+/−)." (PMID 30949516, 2019). "Since no additional effects of glucose were observed on hepatic inflammation or fibrosis in the E3L.GK+/− mice, we suggest that hyperlipidemia rather than hyperglycemia is an initiator of hepatic inflammation and fibrosis." (PMID 30949516, 2019). "Taken together, the results from our study indicate that hyperglycemia per se does not accelerate inflammatory processes in the ApoE−/− GK+/− mouse." (PMID 29760458, 2018). "In addition, hyperglycemia resulted in an increase in glycerol kinase (GK) in WT cells which was absent in MIC26 KO cells." (PMID 39393820, 2024).
Insulin resistance (9 papers, 2009 to 2024). Increased resistance towards insulin, that is, diminished effectiveness of insulin in reducing blood glucose levels. "Furthermore, GK is implicated in insulin metabolism, which in its absence or mutation correlates with increased insulin resistance." (PMID 39199385, 2024). "AQP7 is expressed in adipose tissue where it facilitates the efflux of glycerol, and AQP7 deficiency has been linked to increased glycerol kinase activity and triglyceride accumulation in adipose tissue, leading to obesity and secondary development of insulin resistance." (PMID 29300344, 2018). "This may be due to the expression of AQP7 in adipose tissue where it facilitates the efflux of glycerol, and AQP7 deficiency has been linked to increased glycerol kinase activity and triglyceride accumulation in adipose tissue, leading to obesity and secondary development of insulin resistance." (PMID 32309443, 2020). "The level of GK expression is primarily controlled by insulin and studies have shown that high fat feeding will induce liver insulin resistance with a concomitant reduction in GK expression and activity." (PMID 26790104, 2016). "Furthermore, KA decreased glycerol kinase (GK) expression and increased insulin receptor subtrate 1 (IRS-1) and IRS-2 expressions in the WAT of DIO mice, suggesting that KA partially improved insulin resistance by repairing the impaired insulin signaling pathway caused by DIO." (PMID 38655315, 2024). "The lack of AQP7 is related to the increase of glycerol kinase activity and triglyceride accumulation in adipose tissue, resulting in secondary development of obesity and insulin resistance." (PMID 35245343, 2022).
Obesity (8 papers, 2008 to 2024). Accumulation of substantial excess body fat. "Induction of glycerol kinase and activation of the “futile” cycle could reduce the efflux of free fatty acids, whose levels in serum correlate with obesity-related insulin insensitivity." (PMID 25884368, 2015).
Duchenne muscular dystrophy (6 papers, 2012 to 2025). Duchenne muscular dystrophy (DMD) is a neuromuscular disease characterized by rapidly progressive muscle weakness and wasting due to degeneration of skeletal, smooth and cardiac muscle. "Based on clinical, analytical, and genetic investigations, the patient was diagnosed with Duchenne muscular dystrophy and glycerol kinase deficiency." (PMID 41583306, 2025). "Here, we report a boy with three distinct clinical entities - Duchenne muscular dystrophy, congenital adrenal hypoplasia and glycerol kinase deficiency - due to contiguous gene deletion involving Xp21 genomic location." (PMID 34689766, 2021). "The X-linked type of mutation can be associated with Duchenne muscular dystrophy and/or glycerol kinase deficiency as part of a contiguous gene syndrome." (PMID 23272655, 2012). "Later he was confirmed to have Duchenne muscular dystrophy and glycerol kinase deficiency, as well." (PMID 34689766, 2021). "Based on the presence of Duchenne muscular dystrophy, glycerol kinase deficiency and probable congenital adrenal hypoplasia along with genetic confirmation of deletions involving dystrophin and glycerol kinase genes, the diagnosis of Xp21 contiguous gene deletion syndrome was made." (PMID 34689766, 2021). "When Xp21 is lost, NR0B1, which causes X-linked AHC, GK, which causes glycerol kinase deficiency, and in certain circumstances, DMD are also lost (resulting in Duchenne muscular dystrophy)." (PMID 36497046, 2022). "The blood creatin phosphokinase enzyme and urine glycerol were normal in all cases, indicating that there was no contiguous deletion syndrome with Duchenne muscular dystrophy or glycerol kinase deficiency." (PMID 22761912, 2012).
ocular infection (6 papers, 2013 to 2022). "Our previous studies have established a critical role for SPP binding to gK during HSV-1 ocular infections." (PMID 35100323, 2022). "An interesting sequence of clinically relevant papers show the importance of gK in ocular infection with HSV-1." (PMID 33374862, 2020). "gK also regulates the core fusion complex as it blocks cell fusion when co-expressed with gD, gH/gL, and gB, and in mouse models, gK-deletion mutants fail to spread into neurons after ocular infection." (PMID 29742155, 2018). "Previously, we have shown that a gK-null virus was unable to infect ganglionic neurons and establish latency after ocular infection of mice." (PMID 25350288, 2014). "Capitalizing on our findings that gK is necessary for infection of ganglionic neurons after ocular infection, we explored the use of a gK-null virus as a potential vaccine for HSV-1 and HSV-2 genital infection." (PMID 25350288, 2014). "This hypothesis was supported by the fact that deletion of 37 aa from the amino terminus of gK prevented the virus from infecting ganglionic neurons after ocular infection of mice." (PMID 25350288, 2014). "Specifically, ocular infection of mice previously vaccinated with gK exacerbated corneal immunopathogenesis, while a HSV-1 virus expressing two copies of the gK gene was significantly more virulent than the wild-type virus." (PMID 24165088, 2013). "Ocular infection of mice with a mutant HSV-1 that lacks the N-terminus of gK produced no significant ocular disease symptoms, versus infection with a wild-type strain." (PMID 33374862, 2020). "However, while levels of gB, gK, and ICP0 transcripts were significantly lower in Avil-SPP-/- neurons than control mice on both days 2 and 5 post ocular infection, they did not significantly differ in total RNA isolated from TG on day 2 (Fisher’s exact test) and day 5 (Fisher’s exact test)." (PMID 35100323, 2022).
Glycerol kinase deficiency (5 papers, 2008 to 2025). "SNVs, InDels, and large deletions in the GK gene underlie XLR Glycerol kinase deficiency (GKD) (OMIM #307030) known to cause a metabolic disorder." (PMID 33982443, 2021). "The remaining third includes four genes conserved in nematodes, fly, mouse, and human (zfp-1, R11F4.1, apl-1 and fcd-2) and whose human homologs are linked to disorders (AF10/MLLT10: leukemia, Glycerol kinase: hyperglycerolemia, APP: Alzheimer's, and FANCD2: Fanconi anemia)." (PMID 18752680, 2008). "In humans, glycerol kinase deficiency results in a wide range of phenotypic variability; patients can have severe metabolic and CNS abnormalities, while others possess hyperglycerolemia and glyceroluria with no other apparent phenotype." (PMID 22427807, 2012).
Hepatic steatosis (5 papers, 2014 to 2026). Steatosis is a term used to denote lipid accumulation within hepatocytes. "Marked suppression of two enzymes, SOAT2 and GK, is assumed to play an important role in increasing lipid levels in the affected liver, bringing about hepatic steatosis." (PMID 38419509, 2024). "The contribution of GK to NAFL was investigated in a mouse model of hepatic steatosis induced by HFD." (PMID 39418169, 2024). "Furthermore, GK and PKLR that play a key role in glucose metabolism were repressed in expression and their altered expression is associated with hepatic steatosis." (PMID 25470483, 2014). "In this study, we showed that GK is upregulated in the livers of diet‐induced and genetic mouse models of NAFL and plays a crucial role in the development of hepatic steatosis." (PMID 39418169, 2024).
congenital adrenal hypoplasia (4 papers, 2021 to 2025). "Xp21 gene deletion syndrome is characterized by complex glycerol kinase deficiency, congenital adrenal hypoplasia, intellectual disability, and DMD, while the clinical features depend on the size of the deletion and the number and nature of the encompassed genes." (PMID 40927362, 2025). "In addition to point mutations, there are contiguous deletions of genes in Xp21 with loss of the locus for GK, congenital adrenal hypoplasia (AHC) and/or Duchenne's muscular dystrophy (DMD)." (PMID 36061374, 2022).
hepatocellular carcinoma (4 papers, 2019 to 2024). A malignant tumor that arises from hepatocytes. "Conversely, database data indicate increased GK expression in breast and gastric cancers, but a decrease in hepatocellular carcinoma and renal papillary cell carcinoma, implying a complex, dual role of GK in cancer development." (PMID 38365953, 2024). "Consistent with the open-source database, our experimental results demonstrated that the majority of cancer cells have lower GK expression at both mRNA and protein levels than hepatocellular carcinoma HepG2 cells." (PMID 39199385, 2024). "Sriram’s investigation into glycerol kinase overexpression in rat hepatoma cells sheds light on how GK upregulation alters cellular metabolism, with a particular emphasis on glycerol and lipid metabolic pathways." (PMID 38365953, 2024). "Moreover, GK overexpressed in rat hepatoma induces an excessive consumption of carbon sources." (PMID 39199385, 2024).
corneal infection (3 papers, 2014 to 2025). A viral or bacterial infectious process affecting the cornea. "Also, gK was discovered to be responsible for the spread of HSV from the corneal epithelium to the neurons, suggesting that gK is important for the establishment of latency as corneal infection with HSV-1 that had a mutation in the N-terminus of gK, failed to infect the trigeminal ganglia in mice." (PMID 32457704, 2020).
dermatitis (3 papers, 2014 to 2021). An inflammatory process affecting the skin. "Among all of the tested glycoproteins, only gK exacerbated CS while also causing severe dermatitis and proliferation of the eye." (PMID 34352042, 2021). "In line with the ER stress and the gK-induced collapse of the Golgi apparatus, we have previously shown that a recombinant HSV-1 expressing two additional copies of gK induced severe corneal scarring and dermatitis in different strains of mice." (PMID 24465545, 2014). "Immunization of HSV-1 infected mice with gK, but not with any other known HSV-1 glycoprotein, significantly exacerbates CS, and dermatitis." (PMID 30581441, 2018).
hypertriglyceridemia (3 papers, 2010 to 2025). A laboratory test result indicating elevated triglyceride concentration in the blood. "GKD is a rare genetic disorder characterized by hyperglyceridemia and glycosuria, which are caused by the deletion or mutation of the GK gene." (PMID 39997036, 2025).
insulinoma (3 papers, 2008 to 2019). "Then, we investigated if overexpression of GKRP in insulinoma cells drives nuclear compartmentalization of GK in response to glucose." (PMID 30983961, 2019). "To evaluate this, we performed immunocytochemistry for GK (including immunostaining of GKRP) of insulinoma cell cultured with 0.5 and 50 mM glucose for 30 min." (PMID 30983961, 2019). "As we have confirmed that insulinoma cells are a cellular system free of GKRP, we wonder which patter of compartmentalization of GK can be observed when overexpression of GKRP is induced on this cell line incubated at low and high glucose." (PMID 30983961, 2019). "We evaluated the subcellular localization of GK and GKRP through time in Ad-GKRP transduced insulinoma cells when glucose is increased in the medium." (PMID 30983961, 2019). "Here, we performed a detailed characterization of GK subcellular location in insulinoma cells overexpressing GKRP, switching from low and high glucose concentration, showing that GK is released from the nucleus when glucose concentration increases in the medium." (PMID 30983961, 2019). "In the present work, we characterized insulinoma cells as a GKRP free cellular system that displays cytoplasmic distribution of GK independent of glucose concentrations in the medium." (PMID 30983961, 2019). "In order to understand better the GK and GKRP compartmentalization dynamics observed in tanycytes, we studied the effects of overexpress of Gckr cloned from tanycytes in a cellular model, similar to tanycytes, that is responsive to glucose and express GK; the insulinoma INS-1 (832/13) cell line." (PMID 30983961, 2019). "Additionally, overexpression of GKRP in insulinoma cells, which contain endogenous GK but not GKRP, induce nuclear localization of GK." (PMID 30983961, 2019).
maturity-onset diabetes (3 papers, 2013 to 2023). "Infection studies with glycerol kinase mutant M. tuberculosis reveal that glycerol utilization contributes to the susceptibility of the type 2 diabetes mice." (PMID 37730757, 2023). "Loss of GK alleles results in permanent neonatal diabetes, whereas the heterozygous inactivating mutations of GK lead to maturity-onset diabetes of the young (MODY2)." (PMID 23874448, 2013).